CRP (C-reactive protein)
Diseases named in the same sentence as CRP in open-access papers (continued):
Sharing a sentence is not in itself a finding about the gene and the disease.
COVID-19 (continued). "This study showed that AI-based CXR results for consolidation showed a similar pattern to changes in ESR and CRP results during the treatment of COVID-19 and exhibit potential prognostic value for predicting treatment outcomes." (PMID 37370985, 2023). "Sustained inflammatory state in COVID-19-induced atrial fibrillation documented by marked upregulation of IL-6, CRP (C-reactive protein) and plasma viscosity provides a forewarning for occurrence of thromboembolism and stroke in these patients." (PMID 37120772, 2023). "Activation of this pathway can result in increased CRP levels, which has a significant impact on the severity of COVID-19." (PMID 37520482, 2023). "High levels of inflammatory mediators, such as IL-6, CRP, and neutrophil, have been reported in COVID-19 patients, and this reflects acute inflammatory responses related to cytokine storms." (PMID 37896957, 2023). "According to studies of clinical indicators in patients with COVID-19, there was a significant increase in the level of CRP (on average, from 20 to 50 mg/L)." (PMID 36975366, 2023). "Due to IL-6’s independent correlation with cancer and COVID-19 infection, as well as its close relation to CRP, IL-6 should be considered a potential prognostic indicator for cancer patients with COVID-19 illness, but further trials are needed." (PMID 38127882, 2023). "CRP and leukocyte count were similar between these two groups, whereas procalcitonin levels of the COVID-19 patients were low." (PMID 37515197, 2023). "Compared with healthy controls, the CRP, ferritin, d-dimer and fibrinogen levels were found to be high in all patients with COVID-19; moreover, the CRP, ferritin and d-dimer levels of patients with severe symptoms increased more dramatically (p < 0.05)." (PMID 37112613, 2023). "respectively), higher CRP and ferritin levels, as well as lowerlymphocyte and eosinophil levels, were found to be statisticallysignificant in COVID-19 patients." (PMID 38152003, 2023). "Proteins associated with the excessive inflammatory response (C-reactive protein, CRP), increased blood coagulation (D-dimer), and cell damage (lactate dehydrogenase) have been identified as predictors of COVID-19 severity or mortality." (PMID 40729168, 2023). "In a cohort of 224 COVID-19 patients, elevated PCT was associated with a higher likelihood of co-infection and death, and low CRP levels were strongly predictive of low PCT concentrations with a negative predictive value of almost 100%." (PMID 37510807, 2023). "Specifically, 86.7% of patients with bacterial pneumonia and 62.9% with COVID-19 had elevated levels of CRP compared to 24% of healthy controls." (PMID 38585537, 2023). "A study revealed a significant increase in CRP level in COVID-19 patients with an average of 20 to 50 mg/L, which further increases with disease severity." (PMID 36819137, 2023). "Both WBC and CRP are signs of possible bacterial co-infection, which is known to be a COVID-19 complication occurring more often in critically ill patients." (PMID 37109139, 2023). "The inclusion of this suPAR-based clinical trial in an updated meta-analysis demonstrated that early anakinra administration reduced mortality in hospitalized COVID-19 patients, especially among those with higher initial concentrations of CRP." (PMID 37896812, 2023). "DHT was negatively correlated with D-dimer (r = −0.349, p = 0.013) and CRP (r = −0.283, p = 0.049) levels in post-COVID-19 patients." (PMID 37896963, 2023). "Patients with severe COVID-19 exhibit elevated levels of inflammatory markers such as IL-6, IL-8, C-Reactive Protein (CRP) and lactate dehydrogenase (LDH)." (PMID 37051522, 2023). "Correspondingly, CRP and complement deposits, most notably C1Q, were found in the lungs of deceased COVID-19 patients." (PMID 37626775, 2023). "The CRP/lymphocyte ratio was examined in patients with COVID-19 patients in one study and was described as a good marker in terms of reflecting pneumonia." (PMID 37750127, 2023).
COVID-19 (continued). "Studies have shown that increased CRP levels are positively correlated with the severity of COVID-19." (PMID 38066446, 2023). "During-COVID-19 CRP was positively correlated with during-COVID-19 wake time (r = 0.71, p = 0.01) and time in bed (r = 0.72, p = 0.008)." (PMID 38136035, 2023). "PD-L1 gets dysregulated in COVID-19 patients; increased levels of PD-L1 were found in the serum of these patients which correlated with high lymphopenia and a high amount of C-reactive protein (CRP)." (PMID 37982662, 2023). "C-reactive protein (CRP) is an established inflammatory marker and raised CRP levels are linked to increased disease severity and mortality risk in COVID-19 patients." (PMID 37373898, 2023). "Among COVID-19 patients, the most common predictors of severe prognosis include age, sex and radiomics features, C-reactive protein, lactate dehydrogenase, and lymphocyte counts." (PMID 37950171, 2023). "The aim of our study was to establish the degree of correlation between the parameters of the inflammatory profile (ferritin, fibrinogen, leukocyte count, and CRP) and the degree of severity of COVID-19 in patients with a concomitant diagnosis of neoplasm." (PMID 37623485, 2023). "The mean CRP value in mild COVID-19 patients (32.74 mg/L) was 4 times lower than the one in critical COVID-19 patients (129.06 mg/L)." (PMID 37239895, 2023). "As for inflammation-related factors, including PCT, CRP, and D-dimer they were revealed to be related to the mortality of COVID-19 in our model, which was coincided with previous research." (PMID 37724179, 2023). "In another study, high levels of inflammatory markers such as CRP, erythrocyte sedimentation rate, IL-6, and procalcitonin in COVID-19 patients were reported to indicate hyperinflammatory reactions in COVID-19 patients." (PMID 36919085, 2023). "Open-access RNA-seq databases of COVID-19 patients were mined to illustrate the specific interactions and mechanisms by which CRP contributed to COVID-19 infection." (PMID 38077346, 2023). "Simple and quick-to-obtain biochemical parameters such as red cell distribution width (RDW) and CRP-to-albumin ratio (CAR) provide additional prognostic information to COVID-19 prognostic scores." (PMID 36864814, 2023). "COVID-19 patients were characterized with lymphopenia and the elevated values of neutrophils, C-reactive protein (CRP) and D-dimer that is in accordance with previous data." (PMID 36758022, 2023). "Other biomarkers of systemic inflammation, such as erythrocyte sedimentation rate (ESR), C-reactive protein (CRP), glucose, neutrophils, and neutrophil/lymphocyte ratio, are found to be increased in COVID-19 patients with myocardial injury." (PMID 37009373, 2023). "As adolescents with overweight or obesity (OWOB) present as an even higher risk group, the present study assessed relationships between sleep and CRP levels before and during COVID-19 in adolescents with OWOB." (PMID 38136035, 2023). "The results in this study suggest that LCR is comparable to CRP, but outperformed other inflammatory markers, for prognosticating COVID-19 patients." (PMID 37373898, 2023). "CRP is a protein produced by the liver in response to systemic inflammation, and was also found to be correlated with COVID-19 severity in adults and with multisystemic inflammatory syndrome in children (MIS-C)." (PMID 38188629, 2023). "Nonetheless, we provide weak indirect evidence implicating the severity of COVID-19 illness (elevated C-reactive protein) in the development of CAM." (PMID 36573628, 2023). "The results of univariate analyses showed that age, NEW score, Charlson comorbidity index, IL-6, ferritin, and CRP concentration, WBC and neutrophil count, NLR, LDH on admission, and Ct values ≤30 from SSs were associated with severe COVID-19." (PMID 37213664, 2023). "COVID-19 patients and smokers carriers of one or two copies of the risk allele (rs16969968/A) have high ESR and a positive correlation between fibrinogen and C-reactive protein." (PMID 37372959, 2023).
COVID-19 (continued). "Many studies showed that patients with severe COVID-19 tended to have a higher level of inflammatory cytokines, including white blood cells, neutrophils, procalcitonin, C-reactive protein (CRP), interleukin, ferritin, and so on." (PMID 37147596, 2023). "In one study, severe thrombocytopenia (23,000/μL) and CRP of 1000 mg/L were observed in the co-infected cases that were considered atypical for a clinically mild case of COVID-19." (PMID 37091061, 2023). "A study found that COVID-19 patients with elevated levels of D-dimer (a marker for ischemic stroke) and C-reactive protein (CRP) in the blood had a greater propensity for mortality." (PMID 37163427, 2023). "Higher D-dimer, C-reactive protein, and erythrocyte sedimentation rate and lower hemoglobin were detected in post-COVID-19 patients in another study." (PMID 37373960, 2023). "Among all the markers, the best correlation with the severe form of COVID-19 was observed for the serum CRP levels (R = 0.415, p < 0.001), results confirmed also by the ROC analysis (AUC = 0.720, 95% CI 0.625-0.816, p< 0.0001)." (PMID 37388734, 2023). "CRP, DPP3, and leucocytes were increased in COVID-19 patients with infiltrate above median (each p < 0.05, AUC: CRP 0.82, DPP3 0.70, leucocytes 0.67) compared to infiltrate below median, opposite to non-COVID-19 (each p = n.s)." (PMID 37733154, 2023). "The laboratory parameters seven days after ECMO application were similar, except for a lower d-dimer level, longer PTT, and to some extent higher CRP in the COVID-19 group." (PMID 37366524, 2023). "In this cross-sectional study, we show that gene transcripts of certain cytokines, C-reactive protein, and some cellular enzymes, all involved in the pathogenesis of severe COVID-19, can be measured in the saliva of individuals with the disease." (PMID 37715121, 2023). "For this, we used Fibrin-D-dimer as it is an indicator of clotting disorder and extensively studied in the COVID-19 population, and CRP, a well-established marker of inflammation." (PMID 36862239, 2023). "In COVID-19, the increase in serum CRP in pregnant women has been widely reported, being suggested as an effective method of hospital screening." (PMID 37510647, 2023). "In elderly obese patients with COVID-19, elevated C-reactive protein (CRP), ferritin, and interleukin 6 (IL-6) levels were strongly associated with critical disease." (PMID 37628963, 2023). "Some studies have reported changes in the levels of serum markers in long-term COVID-19 patients, including inflammatory (C-reactive protein (CRP)) and liver markers (alanine aminotransferase (ALT) and aspartate aminotransferase (AST))." (PMID 37047897, 2023). "Considering the possibility of the co-occurrence of bacteraemia with COVID-19, a blood culture should be performed when CRP is ≥ 6.3 or the NLR is ≥ 7.7." (PMID 37939245, 2023). "Some studies even showed that the level of CRP was correlated with poor clinical outcomes among COVID-19 patients." (PMID 37089472, 2023). "HD + COVID-19 patients showed higher inflammation, measured as higher levels of C-reactive protein and IL-6, and lower lymphocytes and higher aspartate aminotransferase in routine clinical tests on the sampling day compared to uninfected HD patients." (PMID 36675231, 2023). "In this study, high levels of the two inflammatory markers CRP and ESR were associated with the severity of COVID-19, thus confirming the results of previous studies." (PMID 38049886, 2023). "COVID-19 patients showed significantly increased levels of CRP+ EVs, which represented 43.0 [19.0–57.0] % of the total count of PS-exposing EVs, vs. 4.0 [3.0–7.5] % in healthy controls." (PMID 38069209, 2023). "The clinical subtype of COVID-19 has been identified using a combination of clinical characteristics and biochemical markers like D-Dimer, C-Reactive Protein and lactic dehydrogenase." (PMID 38014372, 2023).
COVID-19 (continued). "The higher CRP levels observed in COVID-19 patients requiring intensive treatment is the consequence of a systemic hyper-inflammatory state occurring in severe COVID-19 cases." (PMID 37373750, 2023). "Patients with severe COVID-19 show imbalanced responses to infection, immunological cytokine alterations, lymphopenia, systemic inflammation including elevation of C-reactive protein, endothelial dysfunction, hyper-coagulation and tissue damage." (PMID 37958814, 2023). "An ROC analysis was performed to evaluate the diagnostic performance of MDW, CRP, and WBC count in the COVID-19 group and the non-COVID-19 group." (PMID 36973757, 2023). "Lower lymphocyte count and higher CRP in COVID-19 AIS patients are similar to other studies and are associated with a poor prognosis of AIS in COVID-19." (PMID 36862706, 2023). "The differences in CRP levels among the three groups of COVID-19 severity were significant for both female (p < 0.0001) and male (p = 0.0012) subgroups." (PMID 37388734, 2023). "This study aimed to identify hematological parameters such as Leukocyte, Platelets, and Neutrophil count, as well as ALC, PLR, and NLR, along with biochemical parameters namely CRP and D-dimer as predictors for mortality in moderate-severe COVID-19 patients." (PMID 37484181, 2023). "cystatin C and other inflammatory factors such as ferritin, LDH and CRP can help the physician predict the consequences of COVID-19." (PMID 37217858, 2023). "In particular, CRP is associated with in-hospital mortality due to venous thromboembolism and acute kidney injury, and a value of CRP equal to or higher than 40 mg/L is considered life-threatening in COVID-19-hospitalized patients." (PMID 36836679, 2023). "For example, Liu and colleagues reported a 67.9% increase in IL-6 in patients with COVID-19 and found that levels of IL-6 and C-reactive protein (CRP, a biomarker of inflammation) in the severe group was significantly higher than in the mild group." (PMID 36983445, 2023). "CRP, a biomarker produced by the liver and induced by IL-6, is commonly elevated in severe cases of COVID-19, making it a sensitive marker of inflammation and tissue damage." (PMID 37754237, 2023). "Pro-inflammatory chemokines, as well as CRP, were significantly elevated in pediatric patients with neuropsychiatric disorders and COVID-19 compared to controls." (PMID 37189896, 2023). "The findings showed that fibrinogen, D-dimer, and C-reactive protein were significantly greater in the group of patients with severe COVID-19 (p = 0.0001)." (PMID 37390087, 2023). "In COVID-19 patients, IL-6 and CRP levels are also disease severity indicators and predict patient survival." (PMID 37568161, 2023). "Compared to other prognostic parameters for COVID-19, such as interleukin-6, D-dimers, C-reactive protein, and erythrocyte sedimentation rate, NLR is more practical for clinical application since it can easily be obtained via routine blood examinations." (PMID 37101265, 2023). "In multiple studies exploring routine laboratory parameters in COVID-19 patients, increased CRP levels and IL-6 were also reported in severe patients when compared to non-severe patients." (PMID 37624796, 2023). "The cut-off point of CRP ≥ 8.41 mg/dL (AUC = 0.933, sensitivity 98.1%, specificity 72.0%, P = .000) can be used as a predictor of death in COVID-19 in this study." (PMID 37484181, 2023). "Five inflammatory markers were evaluated in the present study, IL-6, IL-8, IL-10, TNF-α, and CRP in hospitalized COVID-19 patients." (PMID 37111039, 2023). "The data of patient #4 revealed the potential for PPHM COVID-19 data to be more informative than IL-6 or CRP data." (PMID 37894092, 2023). "Analysis of the markers of severity related to the SARS-CoV-2, the COVID-19 group revealed low means lymphocytic count, high CRP, and D-dimer tests." (PMID 36644496, 2023).
COVID-19 (continued). "Previously published clinical studies have shown that age, C-reactive protein, and comorbidities play important roles in predicting mortality in patients with COVID-19." (PMID 37559062, 2023). "Other studies showed that obese COVID-19 patients have higher levels of inflammatory mediators, such as D-dimer and C-reactive protein, which also contributed to the severity of COVID-19." (PMID 37047702, 2023). "Our study demonstrated that COVID-19 patients with diabetes had longer hospital stays when they exhibited elevated levels of CRP, IL-6, and CT BoD, as well as decreased PFR." (PMID 37515156, 2023). "This retrospective analysis is consistent with previous reports that D-dimer, leukocyte count, neutrophil count, CRP, and SAA indicate a high risk of severe illness and poor prognosis of COVID-19." (PMID 37965268, 2023). "Among 2989 patients hospitalized for COVID-19 treatment, 19 received the diagnosis of community-acquired bacteraemia, for which CRP ≥ 6.3 was determined to be the cut-off value." (PMID 37939245, 2023). "A significant increase in total serum ferritin, CRP, Procalcitonin and D-dimer was registered in COVID-19 deaths compared to survivors." (PMID 38057707, 2023). "Both the maximum (MAX) CRP value and the rate of CRP rise have also been predictive of COVID-19 severity." (PMID 38003780, 2023). "In another study by Badel on 1810 pediatric patient population with positive PCR test for COVID-19 leukopenia, lymphopenia, elevated ferritin, procalcitonin, and CRP was detected in a laboratory study." (PMID 37942197, 2023). "Glutamine was found to be elevated and positively correlated with C-reactive protein (CRP) levels in patients after COVID-19, suggesting that inflammation persists even in recovered patients." (PMID 37765098, 2023). "The findings demonstrated a significant relationship between high CRP levels and CT severity features in COVID-19 patients at an R value of 0.40." (PMID 37763241, 2023). "Patients with COVID-19-related death had higher levels of leucocyte, neutrophil, D-dimer, troponin, C-reactive protein (CRP), procalcitonin, and ferritin and lower levels of lymphocyte than the survivors." (PMID 38813483, 2023). "Elevated levels of CRP have been observed in patients with COVID-19 and are recognized as an early biomarker for predicting disease severity." (PMID 38585537, 2023). "When looking at the status of LCR in the severe group, it was markedly decreased (25.55 vs 62.23) indicating rising CRP and lymphopenia with the severity of COVID-19." (PMID 37208888, 2023). "Current evidence suggests a significant increase (average 20–50 mg/L) in CRP in almost 86% of COVID-19 patients." (PMID 37365605, 2023). "The CRP scores for COVID-19 patients were 75.7 mg/L (SD = 73.7) in the CKD group and 53.9 mg/L (SD = 59.5) in the non-CKD group." (PMID 38203482, 2023). "Lactate dehydrogenase (LDH), age, red blood cell distribution standard deviation, neutrophils, basophils, and C-reactive protein are the most relevant variables for predicting severe patients' COVID-19 outcomes." (PMID 38125502, 2023). "At the time of diagnosis of persistent COVID-19, all patients were anemic; 6 were lymphopenic; and all had elevated C-reactive protein (CRP)." (PMID 37808896, 2023). "In severe cases of COVID-19 lymphocyte counts are reduced while levels of inflammatory markers such as CRP (C-reactive protein), ferritin, and ESR (Erythrocyte Sedimentation Rate) are increased." (PMID 37754237, 2023). "In our study group (153 COVID-19 patients), the general mortality rate varied form 6.9% for CRP < 100 mg/L to 25.5% for cases with CRP > 100 mg/L." (PMID 37388734, 2023). "Literature-based data mining and construction of the molecular pathways revealed a total of seven genes connecting ADHD with COVID-19, including CRP, PON1, AR, OXT, IL6, TNFSF12, and IL10.." (PMID 38066446, 2023).